ID2 (inhibitor of DNA binding 2)
Diseases named in the same sentence as ID2 in open-access papers (continued):
Sharing a sentence is not in itself a finding about the gene and the disease.
osteosarcoma (7 papers, 2010 to 2024). A usually aggressive malignant bone-forming mesenchymal neoplasm, predominantly affecting adolescents and young adults. "ID2 (inhibitor of DNA binding 2, dominant negative helix-loop-helix binding protein), which was found to be pro-apoptotic in osteosarcoma cells, was exclusively induced in parental cells." (PMID 26573568, 2015). "Four ARGs-BRMS, COL4A2, FGF2, and OGT-were used to develop an RFS-predicting model, whereas seven ARGs-CD24, FASN, MMP2, EIF2AK3, ID2, PPARG, and PIK3R3-were used to develop an OS-predicting model in patients with osteosarcoma." (PMID 38217543, 2024). "For example, it deubiquitinates and stabilizes ID1, ID2 and ID3 proteins to enhance the proliferation of osteosarcoma." (PMID 38366146, 2024). "USP1 deubiquitinates and stabilizes ID1, ID2 and ID3, resulting in the accumulation of ID proteins in osteosarcoma." (PMID 33114077, 2020). "Only CaSki, a cervical cancer cell line, H-2171 (SCLC), and the osteosarcoma cell line U2OS did not express ID2 in remarkable levels." (PMID 20070914, 2010).
Obesity (6 papers, 2012 to 2025). Accumulation of substantial excess body fat. "Id2 expression in adipocytes is positively associated with obesity in mice and humans." (PMID 24023810, 2013). "Taken together these findings clearly reveal the involvement of ID2 in the regulation of glucose/lipid metabolism and in the development of obesity and/or diabetes." (PMID 24023810, 2013). "Transcriptomic analysis further revealed that individuals with obesity had higher expression of cellular senescence-related genes such as ID2, LMNA, and TENT4B in PBMCs compared to lean individuals, with expression levels of these genes significantly decreasing after bariatric surgery." (PMID 40847086, 2025). "Transcriptomic analyses further revealed obesity-induced immune cell senescence through regulation of key genes (ID2, LMNA, CDKN1A), which could be reversed by bariatric surgery." (PMID 40847086, 2025). "In immune cells, ID2 upregulation may represent a protective or compensatory response to obesity-induced inflammation." (PMID 40847086, 2025). "Notably, senescence-associated genes such as ID2, LMNA, CDKN1A, and CTNNB4 were dysregulated in obesity and partially reversed after surgery." (PMID 40847086, 2025). "By exposing human first-trimester trophoblasts to obesity-related plasma factors, we demonstrate that insulin has a direct effect on the regulation of ID2 levels, suggesting that the adverse effects of maternal obesity on preeclampsia begin at an early stage of placental development." (PMID 36768469, 2023). "In contrast to the metabolic phenotype observed in the absence of Id2, elevated expression of Id2 is associated with obesity and/or diabetes." (PMID 24023810, 2013). "We found that MORC3, NUP62, CGAS, ABI3, and RPA2 were highly expressed in lean individuals, where as LMNA, ID2, CDKN1A, TENT4B, MME, and MYC were upregulated in the PBMCs of individuals with obesity." (PMID 40847086, 2025). "New interventions targeting LEP, NOTCH1, SPRY1, PPARG, ID2, and CIDEA gene network, in addition to what already is going on, can be designed for treatment and prevention of both obesity and tumors." (PMID 35395810, 2022). "We investigated how obesity influences preeclampsia in mice lacking ankyrin-repeat-and-SOCS-box-containing-protein 4 (ASB4), which promotes trophoblast differentiation via degrading the inhibitor of DNA-binding protein 2 (ID2)." (PMID 36768469, 2023).
viral infection (6 papers, 2015 to 2025). "In response to acute viral infection, another study found that Tcf1 maintains T follicular T helper (Tfh) cell population by suppressing Blimp1, which promotes Th1-associated effector genes such as T-bet and Id2 expression in Tfh cells." (PMID 35983065, 2022). "Furthermore, Th1 differentiation was significantly blocked by the deficiency of gene Id2 during viral infection." (PMID 30828337, 2019). "In activated T cells, Usp1 interacts with Id2 and Id3, protects the stability of Id2 protein in the context of viral infection, and maintains the proliferative potential and memory phenotype differentiation of virus-specific CD8 effector T cells." (PMID 35983065, 2022). "Cytotoxic effector genes (GZMA, GZMB, ID2, and PLAC8) were enriched in Δ382 SARS-CoV-2 infected patients, coupled with high plasma levels of IFN-γ, TNF-α, and IL-2 during the acute phase of virus infection." (PMID 34716845, 2022). "Id2, therefore reciprocally modulates Th1/Tfh cell differentiation in the course of viral infection and promotes cell-mediated immunity, which does not rely on Tfh cell-mediated humoral response mechanisms to respond to virus infection." (PMID 35983065, 2022). "Id2 is a key regulator of effector CD8 T cell differentiation and maintenance in vivo and has also been shown to promote the differentiation of IFN-γ-producing CD4+ T (so-called Th1) cells upon viral infection." (PMID 32002568, 2020). "Animal studies have confirmed that Id2 preserves the capacity of the pro‐inflammatory Th1 subset to secrete IFN‐γ by directly inhibiting E‐protein binding to the T‐bet gene, thereby suppressing T‐bet expression during the immune effector phase following acute viral infection." (PMID 40051059, 2025).
endometriosis (5 papers, 2017 to 2025). The growth of functional endometrial tissue in anatomic sites outside the uterine body. "As the TATA box lacking genes are intensively dependent to their CAT box region, the role of NF-Y protein in ID2 gene regulation and epigenetic in endometriosis patients is more significant than its binding to the ID1 and ID3 genes." (PMID 30876429, 2019). "The ID2 gene expression was increased in the most advanced stage of endometriosis and in ovarian endometriomas, the PRELP was more expressed in peritoneal lesions, and the SMOC2 was highly expressed in both peritoneal and endometrioma lesions." (PMID 28678915, 2017). "Our results showed higher expression of the ID2 gene in ovarian endometriomas and, considering that its overexpression can inhibit pRb's capacity as a tumor suppressor in cancer cells, it is possible that it also behaves in this way in endometriosis." (PMID 28678915, 2017). "Our time course transcriptomic analyses revealed that BMP ligands and SMAD1/5/4 transcriptional targets, ID2 and ID3, were consistently downregulated in stromal cells from individuals with endometriosis during in vitro decidualization." (PMID 38402336, 2024). "The binding level of NF-Y protein complex to the promoter regions of ID1, ID2, and ID3 genes was displayed through ChIP-Real-Time-PCR and according to the results; it was considerably increased in eutopic group of endometriosis patients in proliferative phase." (PMID 30876429, 2019). "Furthermore, the incorporation of NF-Y complex on CCAAT box region of ID1, ID2, and ID3 promoters was highly enhanced in endometriosis patients." (PMID 30876429, 2019). "Additionally, the expression of ID2, PRELP and SMOC2 genes is similar between the normal endometrium and the eutopic endometrium of women with endometriosis." (PMID 28678915, 2017). "We also observed persistent downregulation of the classical BMP/SMAD1/5/4 target genes, ID2 and ID3, suggesting that impaired BMP signaling was resulting in decreased transcriptional activation by SMAD1/5/4 in stromal cells derived from individuals with endometriosis." (PMID 38402336, 2024). "The expression of the ID2, PRELP and SMOC2 genes was compared between the endometrium of women without endometriosis in the proliferative phase of their menstrual cycle and the eutopic and ectopic endometrium of women with endometriosis in the proliferative phase." (PMID 28678915, 2017). "The canonical SMAD1/5 target genes, ID2 and ID3, were significantly decreased during days 4 and 6 of EPC treatment in the endometrial stromal cells derived from individuals with endometriosis relative to those without." (PMID 38402336, 2024). "In the current study, we compared the expression of the ID2, PRELP and SMOC2 genes in endometriotic lesions (ovarian and peritoneal) and in the eutopic endometrium of women with and without endometriosis in the proliferative phase of their menstrual cycle." (PMID 28678915, 2017).
brain cancer (4 papers, 2017 to 2024). A primary or metastatic malignant neoplasm affecting the brain. "However, it should be noted that the use of AK-778-XXMU, as well as Helichrysetin, another candidate ID2 inhibitor isolated from the Rwandese medicinal plant Helichrysum odoratissimum, to treat brain neoplasm such as GB remain questionable." (PMID 39019900, 2024).
brain tumor (4 papers, 2016 to 2024). "The Id2 gene is also a target for HIF1α and HIF2α, making it part of a positive feedback loop mechanism, at least in models of brain tumor." (PMID 27144179, 2016).
Fanconi anaemia (4 papers, 2018 to 2024). "In cells expressing the p.L605F isoform, there was a significant reduction in the localization of FANCD2, a component of the FANCI-FANCD2 (ID2) binding complex in the Fanconi anemia (FA) pathway, to sites of induced DNA damage." (PMID 39767562, 2024). "Di‐monoubiquitination of the FANCI‐FANCD2 (ID2) complex is a central and crucial step for the repair of DNA interstrand crosslinks via the Fanconi anaemia pathway." (PMID 36385258, 2023). "Localization of FANCD2, part of the FANCI-FANCD2 (ID2) binding complex in the Fanconi anaemia (FA) pathway, to sites of induced DNA damage was severely impeded in cells expressing the p.L605F isoform." (PMID 34861889, 2021).
gastric cancer (4 papers, 2021 to 2024). A primary or metastatic malignant neoplasm involving the stomach. "ID2 is a transcription factor that is overexpressed in many cancers, such as prostate, breast, and gastric cancers." (PMID 36620585, 2022). "Previous studies have shown that inhibitor of DNA binding-2 (ID2) is overexpressed in multiple cancers including gastric cancer." (PMID 34873426, 2021). "However, the regulation of ID2 in gastric cancer remains unclear." (PMID 34873426, 2021). "A study involving 188 patients with gastric cancer (GC) revealed that the mRNA levels and protein levels of USP1 were overexpressed in GC tissue than in adjacent normal tissue, and further analysis indicated that USP1 may promote GC metastasis by upregulating ID2 expression." (PMID 36685967, 2022).
Insulin resistance (4 papers, 2012 to 2024). Increased resistance towards insulin, that is, diminished effectiveness of insulin in reducing blood glucose levels. "The fact that Id2 is up-regulated in the skeletal muscle of obese type II diabetic mice further suggests a role of Id2 in the development of skeletal muscle insulin resistance." (PMID 24023810, 2013). "In this study, we stimulated human first-trimester trophoblasts (HTR8) with insulin at a dose that is comparable to the concentration observed in patients with insulin resistance and observed that ID2 expression in these cells increased in a dose- and time-dependent fashion." (PMID 36768469, 2023).
lung adenocarcinoma (4 papers, 2020 to 2023). A carcinoma that arises from the lung and is characterized by the presence of malignant glandular epithelial cells. "Lung adenocarcinoma cells’ motility, invasion, proliferation, and colony formation can be inhibited by the overexpression of ID2, although this effect can be reversed by silencing ID2." (PMID 36673815, 2023). "For ID2, a decreased expression level was found in lung adenocarcinoma compared with normal samples in the Selamat, Beer, Bhattacharjee and Su datasets." (PMID 32003423, 2020). "Interestingly, RNA-Seq analysis of ID2 knockdown or knockout has recently been performed in lung adenocarcinoma and sarcoma cells." (PMID 37487081, 2023).
lymphoma (4 papers, 2015 to 2024). A malignant (clonal) proliferation of B- lymphocytes or T- lymphocytes which involves the lymph nodes, bone marrow and/or extranodal sites. "Transcription signatures of Id2- and Id3-depleted lymphomas revealed similarities to genetic deficiencies associated with Burkitt lymphoma." (PMID 25691468, 2015). "Mice depleted for Id2 and Id3 expression developed colitis and αβ T-cell lymphomas, and the transcription signatures of Id2- and Id3-depleted lymphomas revealed similarities to genetic deficiencies associated with Burkitt lymphoma." (PMID 25691468, 2015). "Collectively, these observations indicate that depletion of Id2 and Id3 in T-lineage cells leads to increased levels of morbidity caused by the development of lymphoma and/or inflammatory disease." (PMID 25691468, 2015). "We found that Id2- and Id3-deficient lymphomas revealed transcription profiles that overlapped with those derived from Id2- and Id3-deficient CD4SP cells." (PMID 25691468, 2015). "Specifically, ∼2100 genes were differentially expressed in Id2- and Id3-deficient lymphomas versus Id2- and Id3-depleted CD4SP cells." (PMID 25691468, 2015). "Collectively, these data point to a regulatory circuitry that underpins the mechanism by which Id2 and Id3 act to antagonize an innate variant TFH-specific program of gene expression, maintain thymocyte quiescence, and suppress the development of lymphoma." (PMID 25691468, 2015). "Lymphomas depleted for Id2 and Id3 expression displayed elevated levels of c-myc, whereas p19Arf abundance declined." (PMID 25691468, 2015). "Together, the removal of H3K27me3 marks through PRC2 inhibition or depletion results in the upregulation of ACVR1 and the activation of BMP‐ACVR1 signaling, reflected by the phosphorylation of SMAD1/5 and the common upregulation of ID2 or ID3 in EZH2‐mutant lymphoma cells." (PMID 38229201, 2024). "How do lymphomas develop in Id2- and Id3-depleted thymocytes?" (PMID 25691468, 2015). "Several other genes are members of the family of known lymphoma drivers, such as CXCR5, HIST2H3D, ID2 and IRF1." (PMID 33945543, 2021).
pulmonary fibrosis (4 papers, 2018 to 2022). Chronic progressive interstitial lung disorder characterized by the replacement of the lung tissue by connective tissue, leading to progressive dyspnea, respiratory failure, or right heart failure. "The overexpression of Id2 maintains the alveolar epithelial cell phenotype in pulmonary fibrosis, attenuating pulmonary fibrosis." (PMID 35721136, 2022). "Finally, it has been reported that overexpression of Id2 attenuates pulmonary fibrosis by regulating c-Abl and Twist." (PMID 31803053, 2019). "ID-2 protein also has broader anti-fibrotic effects; ID2 transgenic mice show resistance to bleomycin-induced pulmonary fibrosis partially through down-regulation twist." (PMID 29301325, 2018).
autoimmune disease (3 papers, 2018 to 2022). A disorder resulting from loss of function or tissue destruction of an organ or multiple organs, arising from humoral or cellular immune responses of the individual to their own tissue constituents. "These traits are clinically related and colocalized at 13 loci, including sites near genes that regulate eosinophil biology (ETS1 and ID2) and autoimmune disease (KIAA1109 and TAGAP)." (PMID 32600345, 2020). "We propose therefore that Id2 is one such molecule that can serve as an attractive target likely to be modulated to implement therapeutic modalities for Treg related disorders in the context or autoimmune disorders as well as cancer." (PMID 30413714, 2018).
Autoimmunity (3 papers, 2018 to 2023). The occurrence of an immune reaction against the organism's own cells or tissues. "Furthermore, while mice with Treg-specific overexpression of Id2 remains disease free at an early age, steady loss of Foxp3 expression eventually results in severely diminished Treg compartment and results in systemic autoimmunity later in their life." (PMID 30413714, 2018). "Id2 and Id3 are essential for Treg maintenance, and Treg-specific Id2/Id3 double knockout mice are lethal due to multi-organ autoimmunity and show increased Tfr number." (PMID 31434282, 2019). "In mice, Treg cell-specific overexpression of Id2 causes Treg instability, and induces susceptibility to EAE pathogenesis and spontaneous age-related autoimmunity." (PMID 30413714, 2018). "Our findings suggest that controlling Id2 expression may provide a novel approach for effective Treg cell immunotherapies for both autoimmunity and cancer." (PMID 30413714, 2018). "We also identified several genes highly expressed in Th17 cells, including Id2, which mediates the CD4 + T cells immune response, and Fos, which plays a crucial role in autoimmunity and inflammation." (PMID 37344856, 2023).
diabetes (3 papers, 2013 to 2020). "Previous studies on diabetic rats established that the expression of Id2 in renal tubular epithelial cells decreased gradually with the progression of diabetes." (PMID 32636757, 2020).
diabetic nephropathy (3 papers, 2020 to 2022). "Nevertheless, it was still unclear what the exact relationship between Id2 and Twist in diabetic renal fibrosis was and whether oxymatrine exerted protective effects in diabetic nephropathy through both of them." (PMID 32636757, 2020).
Hypertension (3 papers, 2017 to 2023). The presence of chronic increased pressure in the systemic arterial system. "Despite the fact that additional studies should be done to elucidate the role of CD8 + T Lymphocytes in modulating hypertension, it has been shown that mice deficient in transcription factor inhibitor of differentiation (Id2) have altered CD8 + T cell memory and decreased natural killer cells." (PMID 37270484, 2023). "ID2 also plays a major role in the development of hypertension in response to angiotensin II." (PMID 37371111, 2023). "SOCS box-containing 4 could degrade Id2 and mediate vascular differentiation in the placenta, inducing pathology that phenocopies human pre-eclampsia, including hypertension and proteinuria in late-stage pregnant females." (PMID 29348884, 2017).
non-small cell lung carcinoma (3 papers, 2009 to 2021). A group of at least three distinct histological types of lung cancer, including non-small cell squamous cell carcinoma, adenocarcinoma, and large cell carcinoma. "In this work, we investigated, for the first time, the relationship between the expression of ID2 in non-small cell lung cancer (NSCLC) patients and the clinicopathological features and prognosis of these patients." (PMID 19129913, 2009).
ovarian carcinoma (3 papers, 2012 to 2024). A malignant neoplasm originating from the surface ovarian epithelium. "The resulting two main clusters for ovarian cancer cell lines accentuate the expression differences for APOBEC3B, APOBEC3C, and APOBEC3G as well as of ID2 and ID3." (PMID 27527602, 2016). "Furthermore, our analysis of the ovarian cancer data indicates that E2F1, and direct downstream targets of the WNT pathway (survivin, ID2 and vimentin) critical in cell-cycle progression, are up-regulated." (PMID 22548828, 2012).
Renal cyst (3 papers, 2012 to 2024). A fluid filled sac in the kidney. "Enhanced nuclear localization of ID2 has been observed in human and mouse renal cysts, suggesting that ID2 plays a pivotal role in PKD2-mediated cell cycle regulation." (PMID 39451240, 2024). "Enhanced Id2 nuclear localization was found in human and mouse cystic kidneys." (PMID 26110849, 2015). "Increased nuclear localization of Id2 in renal epithelial cells has been reported in kidneys of PKD1 and PKD2 patients, and in Pkd1 knockout mice, which contributes to abnormal epithelial cell proliferation and differentiation in cystic kidneys." (PMID 26110849, 2015).